MPDZ (multiple PDZ domain crumbs cell polarity complex component)
Description:
Member of the NMDAR signaling complex that may play a role in control of AMPAR potentiation and synaptic plasticity in excitatory synapses. Promotes clustering of HT2RC at the cell surface (By similarity).
Synonyms: MUPP1; HYC2
Tractability: Small molecule: it has a high-quality binding pocket. Antibody: UniProt places it where antibodies can reach, with medium confidence; its Gene Ontology location is reachable by antibodies, with medium confidence. PROTAC: ubiquitination databases record sites on it; its protein half-life has been measured.
Gene: Protein-coding gene on chromosome 9 (13,104,620 to 13,279,790, reverse strand). Ensembl gene ENSG00000107186.
Subcellular location: Cell membrane; Apical cell membrane; Postsynaptic density; Cell projection, dendrite; Cell junction, tight junction; Synapse; Synapse, synaptosome
Subcellular location (Human Protein Atlas): Centriolar satellite; Basal body
Gene Ontology:
Molecular function: protein binding
Biological process: tight junction assembly; dendrite development; intracellular protein transport
Cellular component: apicolateral plasma membrane; cytoplasm; apical part of cell; bicellular tight junction; plasma membrane; apical plasma membrane; cytoplasmic vesicle; dendrite; postsynaptic density; Schmidt-Lanterman incisure; subapical complex; synapse
Genetic constraint (gnomAD): Loss-of-function variants: 185 observed, 183.71 expected, observed/expected ratio (o/e) 1.01, 90% interval 0.89 to 1.14. The synonymous counts are far from expectation, so gnomAD's model fits this gene poorly and the ratio says little. Missense variants: 2,833 observed, 2,258.2 expected, observed/expected ratio (o/e) 1.25, 90% interval 1.22 to 1.29. Synonymous variants: 945 observed, 796.19 expected, observed/expected ratio (o/e) 1.19, 90% interval 1.12 to 1.25.
Homologues: Orthologues: chimpanzee MPDZ (99% identical), macaque MPDZ (96% identical), dog MPDZ (92% identical), pig MPDZ (91% identical), rabbit MPDZ (91% identical), rat Mpdz (85% identical), guinea pig MPDZ (84% identical), mouse Mpdz (84% identical), tropical clawed frog mpdz (69% identical), Caenorhabditis elegans frm-5.1 (7% identical), Caenorhabditis elegans frm-5.2 (7% identical). Paralogues in human: PATJ (41% identical), FRMPD2 (10% identical), LNX1 (10% identical), LNX2 (9% identical), STXBP4 (4% identical).
Diseases named in the same sentence as MPDZ in open-access papers:
MPDZ is named in the same sentence as 38 diseases in open-access papers, as found by Europe PMC text mining. Sharing a sentence is not in itself a finding about the gene and the disease. The quoted sentences say what the papers report.
congenital hydrocephalus (14 papers, 2015 to 2025). Hydrocephalus that is present at birth. "LAMB1, MPDZ were analyzed because the mutations in either are known to be associated with congenital hydrocephalus with autosomal recessive genetic inheritance." (PMID 33854687, 2021). "A previous study reported three human families affected with congenital hydrocephalus, harboring MPDZ variants [Family 1, p.(Gln1490Argfs*19); Family 2, p.(Arg744*); p.(Arg1071*); Family 3, p.(Ala1760Thr)]." (PMID 34946889, 2021). "Variations in the CCDC88C gene together with those previously identified in the MPDZ gene represent a new group of emerging diseases causing congenital hydrocephalus." (PMID 34092257, 2021). "A more recent gene linked to congenital hydrocephalus is MPDZ, encoding a large modular scaffold protein that consists of 13 PDZ domains and one L27 domain." (PMID 30518636, 2019). "Though congenital hydrocephalus is heritable, it has been linked only to eight genes, one of which is MPDZ." (PMID 30518636, 2019). "MPDZ gene variants have been reported to be associated with congenital hydrocephalus." (PMID 36429029, 2022). "Most of studies associated with the function of the MPDZ gene were focused on the cytoskeleton, protein complex formation, signal transduction, cell polarity, cell osmotic pressure reactions and the causes of severe congenital hydrocephalus." (PMID 29108259, 2017). "The MPDZ gene, located on chromosome 9p24-p22, was first involved in severe non-syndromic congenital hydrocephalus by the characterization of a homozygous nonsense variant in exon 6 in two Saudi consanguineous families, c.628C > T; p.(Gln210*), suggesting a founder effect." (PMID 28460636, 2017). "Mutations in the tight junction gene MPDZ (absent in the 129 brain but present or marginal in B6 brains) also result in non-syndromic congenital hydrocephalus in patients." (PMID 30190587, 2018). "Genetic heterogeneity of congenital hydrocephalus is observed: mutations in the CCDC88C gene [MIM:611204] on chromosome 14 and in the MPDZ gene [MIM:603785] on chromosome 9 are responsible for autosomal recessive hydrocephalus (respectively HYC1 [MIM:236600] and HYC2 [MIM:615219])." (PMID 26452345, 2015).
Hydrocephalus (14 papers, 2017 to 2025). Hydrocephalus is an active distension of the ventricular system of the brain resulting from inadequate passage of CSF from its point of production within the cerebral ventricles to its point of absorption into the systemic circulation. "Isolated hydrocephalus can also be caused by biallelic pathogenic variants of the MPDZ gene, heretofore reported in 5 consanguineous families with isolated hydrocephalus inherited in an autosomal recessive manner." (PMID 40892511, 2025). "LCAM1 and MPDZ (MUPP1) are the only known human gene loci associated with non‐syndromic hydrocephalus." (PMID 28500065, 2017). "More recently, mutations in other genes have been reported to be causative for non-syndromic hydrocephalus, notably in the MPDZ gene (MIM#615219)." (PMID 28460636, 2017). "Moreover, a previous report on compound heterozygous variants (p.Gly132Ser and p.Leu582Val) of the MPDZ gene also highlighted an association with the congenital communicating hydrocephalus phenotype." (PMID 36429029, 2022). "More recently, a founder mutation has also been reported in the MPDZ gene in foetuses presenting massive hydrocephalus, but the neuropathology remains unknown." (PMID 28460636, 2017). "MPDZ mutations impair intercellular junctions, while CCDC88C mutations compromise cytoskeletal stability and formation, collectively leading to hydrocephalus." (PMID 39839745, 2024). "Recently, two autosomal recessive forms of hydrocephalus have been linked to mutations in MPDZ and CCDC88C that encode a tight junction protein (MUPP-1) and a regulator of cell migration (DAPLE), respectively." (PMID 35096710, 2021). "Although numerous genes have been found to be associated with the development of hydrocephalus in animal studies, only six genes have been definitively proven to be closely related to congenital hydrocephalus in humans: L1CAM, AP1S2, MPDZ, FOXJ1, SMARCC1, and CCDC88C." (PMID 39839745, 2024). "Nonsyndromic hydrocephalus includes the classical X‐linked type associated with mutations in L1CAM (MIM 307000) and autosomal recessive hydrocephalus related to the gene CCDC88C (HYC1, MIM 236600), MPDZ (HYC2, MIM 615219), and WDR81 (HYC3, MIM 617967)." (PMID 33724704, 2021). "Therefore, any disruption of TJs and particularly abnormal cell-cell adhesion by PDZ proteins including MPDZ (also named MUPP1 which is strongly expressed in choroid plexuses) most likely alters the distribution of TJs that leads to uncontrolled secretion of CSF and hydrocephalus." (PMID 28460636, 2017). "Two of the known human hydrocephalus genes, CCDC88C and MPDZ, were identified in the microarray." (PMID 30190587, 2018).
keratoconus (8 papers, 2014 to 2023). A degenerative, structural disorder of the eye, characterized by a cone-shaped protrusion of the cornea. "We found that rs1536482 near the COL5A1 gene, rs2721051 near the FOXO1 gene, and rs1324183 near the MPDZ gene were significantly associated with keratoconus in a Russian cohort." (PMID 34625056, 2021). "This study aimed to investigate the replication of three SNPs (rs1536482 near the COL5A1 gene, rs2721051 near the FOXO1 gene, rs1324183 near the MPDZ gene) with keratoconus in the largest sample of patients from Russia." (PMID 34625056, 2021). "The minor allele distribution was significantly different (p-value < 0.05) between the keratoconus and main control groups for all three SNPs: rs1536482 near the COL5A1 gene, rs2721051 near the FOXO1 gene, and the rs1324183 minor allele near the MPDZ gene." (PMID 34625056, 2021). "The purpose of this study was to validate whether three reported keratoconus-associated SNPs (rs1536482 near the COL5A1 gene, rs2721051 near the FOXO1 gene, rs1324183 near the MPDZ gene) are also actual for a Russian cohort of patients." (PMID 34625056, 2021). "This meta-analysis identified six SNPs within or nearby FOXO1 (rs2721051), FNDC3B (rs4894535), RXRA-COL5A1 (rs1536482), MPDZ-NFIB (rs1324183), COL5A1 (rs7044529), and BANP-ZNF469 (rs9938149) genes/loci that were strongly associated with the risk of keratoconus." (PMID 25254113, 2014). "Similarly, other candidate genes identified by GWAS including HGF, RAB3GAP1, LOX, MPDZ, NFIB, BANP, and ZNF469 may be important risk factors for keratoconus and require replication studies in other populations." (PMID 25254113, 2014). "Overall, we found a significant negative correlation of effect sizes across CCT and keratoconus (r = −0.62, P = 5.30 × 10−5), this correlation was largely unchanged if the known SNPs in ZNF469, FOXO1, COL5A1 and MPDZ/NFIB were removed from the analysis (r = −0.61, P = 2.04 × 10−4)." (PMID 29760442, 2018).
Leber congenital amaurosis (4 papers, 2010 to 2025). Leber congenital amaurosis (LCA) is a retinal dystrophy defined by blindness and responses to electrophysiological stimulation (Ganzfeld electroretinogram (ERG)) below threshold, associated with severe visual impairment within the first year of life. "An MPDZ mutation was identified as the cause of an inherited retinal dysplasia and degeneration in chicken, and MPDZ variants were identified in human patients with retinitis pigmentosa and Leber congenital amaurosis that are diseases of the eye." (PMID 40650235, 2025).
deafness (3 papers, 2021 to 2023). An inherited or acquired condition characterized by the complete loss of the ability to hear from one or both ears. "In three (III:3, IV:2, and IV:3) of the remaining four affected individuals, although we found rare and predicted damaging variants of known deafness genes (MPDZ, KCNQ4), however, these variants require further experimental studies to validate their pathogenic impact on the encoded proteins." (PMID 34946889, 2021). "Two of the affected individuals were homozygous for the variants in genes, GJB2, MPDZ, known to cause recessively inherited hearing loss, while other two affected individuals were heterozygous for a variant in KCNQ4, a dominant deafness-causing genes." (PMID 34946889, 2021). "This study presents a HL family GCUFAHL38, in which five different deafness genes (GJB2, SLC26A4, CDH23, MPDZ, KCNQ4) rare variants were co-segregating in different configurations, and thus further highlights the genetic complexity of hearing disorders in highly inbred families." (PMID 34946889, 2021).
glioma (2 papers, 2024). A benign or malignant brain and spinal cord tumor that arises from glial cells (astrocytes, oligodendrocytes, ependymal cells). "They found that low mRNA expression of Multiple PDZ Domain Crumbs Cell Polarity Complex Component (MPDZ) was significantly correlated with worse overall survival in both IDHwt and IDH mutated gliomas." (PMID 39132508, 2024). "Low MPDZ mRNA expression was significantly correlated with worse overall survival in both IDHwt and IDH-mutated gliomas.These results suggest that MPDZ alteration may contribute to the systematic resistance of these tumours." (PMID 39132508, 2024).
breast carcinoma (1 paper, 2017). "The expression of MPDZ in breast cancer tissue was substantially lower than that in the normal mucosa and is correlated with cancer progression and aggression." (PMID 29108259, 2017). "However, several reports showed that MPDZ participated in nasopharyngeal carcinoma and breast cancer tumorigenesis." (PMID 29108259, 2017).
Charcot-Marie-Tooth disease type 4A (1 paper, 2024). "Four of these decedents had compound heterozygous P/LP/VUS variants in genes associated with recessive disorders, including CFTR (cystic fibrosis), BCKDHA (maple syrup urine disease), MPDZ (congenital hydrocephalus-2), and GDAP1 (Charcot-Marie-Tooth disease, type 4A)." (PMID 38229148, 2024).
colorectal cancer (1 paper, 2022). A primary or metastatic malignant neoplasm that affects the colon or rectum. "Collectively all these results reveal that the RIMKLB gene has a positive association and correlation with AKT3, MPDZ, PKD2, and MAP1B to upregulate the gene expression to induce the development of colorectal cancer." (PMID 35444692, 2022).
epilepsy (1 paper, 2024). A brain disorder characterized by episodes of abnormally increased neuronal discharge resulting in transient episodes of sensory or motor neurological dysfunction, or psychic dysfunction. "MPDZ variants were identified in six unrelated families with epilepsy." (PMID 38292201, 2024). "PDZ3 of MPDZ interacts with DAPLE (encoded by CCDC88C) that is associated with neurodegenerative diseases, congenital hydrocephalus, and epilepsy in an autosomal dominant/recessive inheritance, potentially explaining the heterozygous variants associated with febrile seizures." (PMID 38292201, 2024). "PDZ10 of MPDZ interacts with the 5-hydroxytryptamine type 2C receptors (HTR2C), which presented epilepsy phenotypes in knockout mice model." (PMID 38292201, 2024).
lipoma (1 paper, 2016). A benign, usually painless, well-circumscribed lipomatous tumor composed of adipose tissue. "HMG2A-NFIB fusions have been reported in lipomas while other tumour-associated translocations involving NFIB include MPDZ-NFIB, NFIB-FREM, NFIB-HEATR5B, NFIB-STRN and NFIB-ZDHHC21." (PMID 27083054, 2016).
lung carcinoma (1 paper, 2024). "In addition, MPDZ has also been reported to exert an inhibitory effect on lung cancer by inducing the dephosphorylation of YAP, and its specific expression can also serve as an independent predictive factor for the diagnosis of lung cancer and other cancers." (PMID 39877345, 2024).
macular coloboma (1 paper, 2022). "Taking together the genetic findings and the phenotypes of the corresponding zebrafish models, the novel compound heterozygous variation of the MPDZ gene was evidenced to cause macular coloboma via both recessive negative and loss-of-function effects, respectively." (PMID 36429029, 2022). "It is worth noting that some HYC2 cases with MPDZ truncation variations also presented iris defects and retinal abnormalities, but the proband in our study only showed isolated macular coloboma without HYC2." (PMID 36429029, 2022).
metastatic cancer (1 paper, 2016). A carcinoma which has spread from the original site of growth to another anatomic site. "Two amplified genes had contradictory functions to being overexpressed in metastatic cancer, SCEL (a keratinocyte differentiation factor), and MPDZ (a cell adhesion factor)." (PMID 27136531, 2016).
retinal disease (1 paper, 2010). "This animal model may therefore offer valuable insights into the pathogenesis of RP, and the potential involvement of MPDZ mutations in human inherited retinal disease is currently being investigated." (PMID 20069063, 2010).
Ventriculomegaly (1 paper, 2025). An increase in size of the ventricular system of the brain. "Regarding postnatal outcomes, our cases presenting with pathogenic variants of MPDZ (Family 1) showed an intrafamilial variability of both severity of the ventriculomegaly and outcome, ranging from mild delays to normal neurodevelopment." (PMID 40565599, 2025). "Among these, MPDZ variants have been reported to cause severe ventriculomegaly inherited in an autosomal recessive manner (OMIM#615219)." (PMID 40565599, 2025).
tumor (7 papers, 2016 to 2025). "Tumor angiogenesis was enhanced upon endothelial-specific inactivation of MPDZ leading to an excessively branched and poorly functional vessel network resulting in tumor hypoxia." (PMID 29620522, 2018). "The molecular link between the deletion of MPDZ and cancer-specific outcomes suggests that MPDZ is a potential tumor suppressor gene in ccRCC." (PMID 29108259, 2017). "These genetic changes suggest that MPDZ is a potential tumor suppressor gene in ccRCC, which provides a novel tumor molecular marker for diagnosis, prognosis and therapy of patients with ccRCC." (PMID 29108259, 2017). "Interestingly, there had the positive nuclear staining of MPDZ in partly tissue samples particularly in tumor samples." (PMID 29108259, 2017). "Furthermore, immunohistochemical analysis by tissue microarray showed that MPDZ was expressed at lower levels in tumor tissues compared with adjacent tissues (P<0.01)." (PMID 29108259, 2017). "However, its role in tumor development has not been studied, except in one study that suggested that endothelial-specific inactivation of MPDZ leads to an excessively branched and poorly functional vessel network, resulting in tumor hypoxia and enhanced tumor angiogenesis." (PMID 40457491, 2025). "Upon analyzing the expression of 11 model genes in prostate PRAD, we observed significant differential expression of eight genes (MYADM, MPDZ, LTBP2, DENND4C, PROK1, DDIT4, IGFBP3, and CFD) between normal and tumor tissues." (PMID 38898043, 2024).
cancer (3 papers, 2017 to 2024). A tumor composed of atypical neoplastic, often pleomorphic cells that invade other tissues. "We would also study the specific mechanism of MPDZ that has different subcellular localization in cancer in future research." (PMID 29108259, 2017). "Because the deletion of MPDZ is an important regulation mechanism for its transcriptional expression, we further investigated MPDZ expression levels in 72 carcinoma tissues and adjacent tissues." (PMID 29108259, 2017).
neurological diseases (1 paper, 2023).
MPDZ also shares sentences with these, for which no sentence is quoted: autism spectrum disorder (2 papers); communicating hydrocephalus (2); retinitis pigmentosa (2); cervical cancer (1); clear cell renal cell carcinoma (1); cystic fibrosis (1); hearing disorder (1); hematological disease (1); Hyperglycemia (1); maple syrup urine disease (1); mesothelioma (1); nasopharyngeal carcinoma (1); nephrotic syndrome (1); neurodegenerative disease (1); non-communicating hydrocephalus (1); nonsyndromic hearing impairment (1); Obesity (1); thoracic aortic aneurysm (1); Warburg micro syndrome (1).